KRT19 (keratin 19)
Diseases named in the same sentence as KRT19 in open-access papers (continued):
Sharing a sentence is not in itself a finding about the gene and the disease.
infection (19 papers, 2010 to 2025). The state of being infected such as from the introduction of a foreign agent such as serum, vaccine, antigenic substance or organism. "The increased expression of KRT19 in lactobacilli groups can contribute to more opportunities for living cells to adhere to the epithelial and exclusively inhibit pathogen infection." (PMID 28616225, 2017). "Similarly, relatively little infection was found in the cytokeratin 19 (CK19) positive pancreatic epithelium." (PMID 39348381, 2024). "Other observed changes in cytokeratin expression which do not usually form part of a blistering signature include the upregulation of KRT15 and KRT19 which are associated with stem cells in adnexal skin compartments, a region which histologically is positive for VZV early on in infection." (PMID 24497829, 2014). "Genes for epithelial cell markers such as cytokeratins 14, 18 and 19 (KRT14, KRT18, KRT19), E-cadherin (CDH1) and epithelial cell adhesion molecule (EPCAM) showed the highest expression at 0 hpi and decreased post-infection." (PMID 34740333, 2021).
breast (6 papers, 2009 to 2025). "Consequently, we selected eight statistically significant TACTs—EPCAM, KRT19, ERBB2, MKI67, MCAM, FOXA2, SNAI2, and NPTN—which we designated as colorectal TACTs (C-TACTs)." (PMID 40003943, 2025).
Head and Neck Tumors (2 papers, 2019 to 2023). "The 4th edition of the World Health Organization Classification of Head and Neck Tumors (WHO-HNT) indicates that NPPA with positive expression of cytokeratin 19 (CK19) and TTF-1 and negative expression of TG is called TL-LGNPPA." (PMID 36705380, 2023).
neurological diseases (2 papers, 2017 to 2020). "We measured carcinoembryonic antigen (CEA) and cytokeratin 19 fragments (CYFRA 21-1) in paired samples of CSF and serum from patients with LM and patients with nonmalignant neurological diseases (NMNDs) as controls." (PMID 28298807, 2017).
KRT19 also shares sentences with these, for which no sentence is quoted: papillary carcinoma (15 papers); cholestasis (12); melanoma (9); endometrial cancer (8); liver cirrhosis (8); thyroid nodule (8); odontogenic cyst (6); acute pancreatitis (5); neuroendocrine tumors (5); adenocarcinoma of the gallbladder (4); benign tumor (4); colitis (4); endometrioid adenocarcinoma (4); gastric adenocarcinoma (4); metastasis (4); primary sclerosing cholangitis (4); anaplastic thyroid carcinoma (3); cervical intraepithelial neoplasia (3); cervical tumor (3); cholangioma (3); chronic hepatitis C (3); endocrine pancreatic tumor (3); gallbladder cancer (3); metastatic carcinoma (3); odontogenic tumors (3); primary biliary cirrhosis (3); small cell carcinoma (3); tuberculosis (3); ulcerative colitis (3); alveolar rhabdomyosarcoma (2).
A further 181 diseases each share a sentence with KRT19 in 2 papers or fewer.